SERBP1 (SERPINE1 mRNA binding protein 1)
Diseases named in the same sentence as SERBP1 in open-access papers (continued):
Sharing a sentence is not in itself a finding about the gene and the disease.
ischemic stroke (3 papers, 2023 to 2025). A stroke disorder caused by obstruction of blood flow to the brain, due to thrombotic (local blood clot formation) or embolic (due to a blood clot or other material traveling from another site) event. "In our previous studies, we revealed an association between the risk of ischemic stroke and the genes C9orf16, C19orf53, SERBP1, and SERF2 using a population genetics-based approach." (PMID 40459864, 2025). "The present pilot study investigated whether SERBP1 SNPs are associated with the risk and clinical manifestations of ischemic stroke (IS)." (PMID 37240062, 2023). "In order to address the involvement of Hero-proteins in the pathobiology of CVDs, we have previously conducted a genetic study exploring the associations of the genes C19orf53, SERBP1, SERF2, and C9orf16 (BBLN) with ischemic stroke." (PMID 40459864, 2025). "In our prior research, we investigated the impact of four Hero genes—C9orf16 (Hero9), SERBP1 (Hero45), SERF2 (Hero7), and C19orf53 (Hero11) —on ischemic stroke risk, finding a notable association between these genes and the disease." (PMID 39595169, 2024).
neuroblastoma (3 papers, 2007 to 2022). Neuroblastoma (NB) is the most common solid, extracranial childhood tumor. "Searching for Ago2 partners by immunoprecipitation and LC-MS/MS analysis, we isolated among other proteins the Serpine mRNA binding protein 1 (SERBP1) from SH-SY5Y neuroblastoma cells." (PMID 35326503, 2022). "Both Myc-SERBP1 and FLAG-Ago2 plasmids were co-transfected in human neuroblastoma cells SH-SY5Y; as a control we performed a co-transfection using a plasmid that expressed only c-Myc tag and the plasmid containing FLAG-Ago2." (PMID 35326503, 2022).
Obesity (3 papers, 2023 to 2025). Accumulation of substantial excess body fat. "PAI-1 levels, regulated by SERBP1, positively correlate with obesity and are significantly reduced by weight loss in obese individuals." (PMID 37240062, 2023). "Next, we aimed to elucidate whether the observed preventive action of elocalcitol on HFD-induced obesity is linked to the suppression of lipogenesis mediated via the SERBP-1 pathway." (PMID 39898321, 2024). "This relation can be explained in terms of connections between obesity, leptin and the level of SERBP1 expression." (PMID 37240062, 2023).
renal fibrosis (3 papers, 2021 to 2026). A final common manifestation of a wide variety of chronic kidney diseases characterized by glomerulosclerosis and tubulointerstitial fibrosis. "As per a recent study, circEIF4G2 has been shown to increase renal fibrosis through the miR‐218/SERBP1 pathway, while overexpression of circRNA_010383 has been shown to inhibit renal fibrosis and proteinuria in a mouse model." (PMID 41405560, 2026). "We report that circEIF4G2 promoted renal fibrosis by regulating the miR‐218/SERBP1 pathway, which provides new insights into the pathogenesis of DN." (PMID 33615661, 2022). "CircEIF4G2 promotes renal fibrosis via the miR-218/SERBP1 pathway." (PMID 35222519, 2021). "Finally, we assessed the effects of miR‐218 and SERBP1 on renal fibrosis." (PMID 33615661, 2022).
breast tumor (2 papers, 2012 to 2021). "Furthermore, SERBP1 may represent a novel breast tumour marker with prognostic significance." (PMID 23236990, 2012).
colon cancer (2 papers, 2008 to 2022). "Based on the finding that C8orf4 was higher expressed in normal mucosa than in colon cancer cell lines with colon cancer metastases, we predicted that C8orf4 mediated by SERBP1 played a role in colon cell differentiation or growth regulation." (PMID 36213507, 2022). "Many processes involving SERBP1 are relevant to colon cancer cells." (PMID 36213507, 2022).
liver cancer (2 papers, 2022 to 2025). An epithelial or non-epithelial malignant neoplasm that arises from the liver. "In liver cancer, the long non-coding RNA (lncRNA) circBACH1 can “sponge” miR-656-3p, relieving its translational inhibition on SERBP1 mRNA, leading to the up-regulation of SERBP1 expression." (PMID 41227349, 2025).
lung carcinoma (2 papers, 2020 to 2022). "From the result, SERBP1 (SERPINE1 mRNA binding protein 1), which was previously discovered to be differentially expressed in lung cancer, was found to have relatively high potential to bind with LINC01468." (PMID 35387981, 2022).
pancreatic cancer (2 papers, 2020 to 2021). "Zhao and his partners declared that PVT1 was a sponge of miR-448 to upregulate SERBP1, thereby facilitating proliferation and migration of pancreatic cancer cells." (PMID 33817293, 2021).
prostate carcinoma (2 papers, 2018 to 2020). A carcinoma that arises from epithelial cells of the prostate gland. "In addition, the activation of SERBP1 promotes cell proliferation, migration, and invasion in prostate cancer." (PMID 32201535, 2020).
viral infection (2 papers, 2021 to 2025). "In conclusion, as a multifunctional RNA-binding protein, SERBP1 plays a key role in various fields such as cellular stress, tumors, reproduction, nerves, and viral infection." (PMID 41227349, 2025). "SERBP1 plays a core role in five major physiological and pathological processes including cellular stress response, tumorigenesis, reproductive regulation, nervous system function, and viral infection, achieving diverse biological effects by regulating different key cellular processes." (PMID 41227349, 2025).
acute myeloid leukemia (1 paper, 2022). Acute myeloid leukemia (AML) is a group of neoplasms arising from precursor cells committed to the myeloid cell-line differentiation. "In no cancer did SERBP1 show significantly lower value, although it was highly expressed in acute myeloid leukemia (LAML) normal tissues." (PMID 36213507, 2022).
Alzheimer disease (1 paper, 2025). A progressive, neurodegenerative disease characterized by loss of function and death of nerve cells in several areas of the brain leading to loss of cognitive function such as memory and language. "SERBP1 has been observed in Tau aggregates in Alzheimer’s disease (AD) brains and is part of a group of 261 proteins detected in several studies that examined the composition of Tau aggregates." (PMID 39937575, 2025). "In the case of Alzheimer’s disease, increased expression of SERBP1 and its presence in pathological aggregates hint at a potential involvement." (PMID 39937575, 2025).
brain tumour (1 paper, 2023). "Alterations in RBP expression levels and function have been associated with neurological disorders (e.g. HNRNPA1, MATR3, TIA1, and TARDBP and brain tumour development (e.g. Musashi1, SERBP1, PTB and HuR." (PMID 37294214, 2023).
cervical cancer (1 paper, 2023). A primary or metastatic malignant neoplasm involving the cervix. "miR-362-3p was previously identified as a tumor suppressor gene, and the downregulation of miR-362-3p resulted in tumor progression, migration, and invasion by targeting SERBP1, p130Cas, and BCAP31 in ovarian, breast, and cervical cancers, respectively." (PMID 37240034, 2023).
chronic lymphocytic leukemia (1 paper, 2012). "Increased PAI-RBP1 (the protein of the gene SERBP1 (vig-1)) expression was found in chronic lymphocytic leukemia and correlated with tumor progression in epithelial ovarian cancer." (PMID 23155442, 2012).
COVID-19 (1 paper, 2024). A disease caused by infection with severe acute respiratory syndrome coronavirus 2. "Taking into account the therapeutic effect of Jusvinza for AR and COVID-19 treatments, validating whether NCL and SERBP1 down-regulation in Jusvinza-treated neutrophils is related to impairment of mtDNA internalization and decreased PAI-1 levels, respectively, could be of interest." (PMID 39767648, 2024).
ductal carcinoma in situ (1 paper, 2012). "In ductal carcinoma in situ SERBP1 was expressed moderately in the nucleus as well as in the cytoplasm." (PMID 23236990, 2012).
epilepsy (1 paper, 2025). A brain disorder characterized by episodes of abnormally increased neuronal discharge resulting in transient episodes of sensory or motor neurological dysfunction, or psychic dysfunction. "In addition, the expression of SERBP1 is down-regulated by 38% in epilepsy model mice, and restoring SERBP1 expression can reduce the frequency of epileptic seizures by decreasing the KCC2 level, confirming the potential therapeutic value of SERBP1 in nervous system diseases." (PMID 41227349, 2025).
Fibroadenoma (1 paper, 2021). A benign tumor of the breast characterized by the presence of stromal and epithelial elements. "In women with fibroadenoma, an autoantibody response occurred against VPS35 (p = 0.007 compared to control women), SERBP1 (p < 0.0001 compared to control women), KRT8 (p = 0.03 compared to control women), and PDIA6 (p = 0.003 compared to control women)." (PMID 33976232, 2021).
Hepatic steatosis (1 paper, 2025). Steatosis is a term used to denote lipid accumulation within hepatocytes. "In the SERBP1-knockdown NASH mouse model, the degree of hepatic steatosis is reduced by 60%, and the expression of inflammatory factors (TNF-α and IL-6) is decreased by 45%, confirming the pro-pathological role of SERBP1 in NASH." (PMID 41227349, 2025).
invasive breast carcinoma (1 paper, 2012). A carcinoma that infiltrates the breast parenchyma. "In invasive breast carcinomas SERBP1 expression was generally very differential with low (ductal type) to intense expression pattern in the nucleus as well as in the cytoplasm of the mammary epithelial cells (ductal type)." (PMID 23236990, 2012).
ischemic heart disease (1 paper, 2025). "Single Nucleotide Polymorphisms (SNPs) of SERBP1 are associated with the risk of ischemic heart disease." (PMID 41227349, 2025).
latent infection (1 paper, 2022). "Both activities of SERBP1 could lend themselves to functions which might be predicted to be required for the maintenance of a latent infection." (PMID 36504797, 2022). "It would be of interest to determine whether these other herpesviruses also use SERBP1 as a scaffold to recruit both KAP1 and CHD3 to their genomes to initiate and maintain a repressive chromatin structure during latent infection." (PMID 36504797, 2022). "We now show that the cellular protein Plasminogen activator inhibitor 1 RNA-binding protein (SERBP1), a known interactor of CHD3, is significantly upregulated during HCMV latency and that this protein is required for MIEP suppression during latent infection of myeloid cells." (PMID 36504797, 2022).
muscle atrophy (1 paper, 2019). The loss of muscle tissue due to inactivity or disease. "Serbp1, a plasminogen activator inhibitor 1 (PAI-1) mRNA binding protein that inhibits the stability of PAI-1 mRNA, causes increases in age-associated muscle atrophy, fibrosis, and impairs muscle regeneration, by binding to its cyclic nucleotide-responsive sequence." (PMID 31241467, 2019).
triple-negative breast carcinoma (1 paper, 2025). An invasive breast carcinoma which is negative for expression of estrogen receptor (ER), progesterone receptor (PR), and human epidermal growth factor receptor 2 (HER2). "In triple-negative breast cancer (TNBC), SERBP1 inhibits tumor progression by regulating alternative splicing of genes: SERBP1 interacts with the splicing factor SF3B1 to promote the exon 3 skipping splicing of the ME3 (Methylmalonyl-CoA Epimerase) gene." (PMID 41227349, 2025).
tumor (24 papers, 2012 to 2025). "In terms of clinical transformation, the diagnostic value of SERBP1 as a tumor marker still needs to be verified by multi-center, large-sample studies." (PMID 41227349, 2025). "The higher expression levels of SERBP1 has been associated to higher grading of the tumor stages, making SERBP1 a prognostic predictor candidate and candidate gene involved in the tumorigenesis process and resistance to anti-cancer drugs." (PMID 33245729, 2020). "RNA binding protein SERBP1, which regulates mRNA translation, has been identified as a target of the tumor suppressor miR-218 in HCC and confirmed associated with cell migration/invasion and epithelial mesenchymal transition." (PMID 32873282, 2020). "A suggestive novel gene, SERBP1, encodes a B-cell antigen, shown to predict anti-tumor immune response." (PMID 29293537, 2018). "In vitro and in vivo studies have shown that the expression level of SERBP1 impacts various cancer-related phenotypes, including stemness, neuronal differentiation, and tumor growth, while the knockdown of SERBP1 affects the expression of genes linked to neurogenesis and synaptogenesis." (PMID 38698775, 2024). "SERBP1’s role in regulating a gene network implicated in metabolic pathways relevant to cancer cells is likely to be a key contributor to its broad impact on cancer phenotypes and tumor growth." (PMID 32762776, 2020). "Three somatic mutations were detected in the tumor of P04: one nonsense mutation in SERBP1 (c.1117C > T, p.Arg373*) with 97.26% of VAF, and missense mutations in WTAP (c.485G > A, p.Arg162Gln) and PHF5A (c.305G > A, p.Arg102His) with VAFs of 98.63% and 97.22%, respectively." (PMID 32592321, 2020). "Moreover, the mRNA binding protein SERBP1, associated to the 40S subunit of active ribosomes in normal and tumor cells, binds to CtIP mRNA and promotes its translation specifically in S phase by binding to its 3′-UTR." (PMID 32392243, 2020). "SERBP1 exerts a tumor-type-dependent pro-cancer effect by regulating specific target mRNAs in different tumors." (PMID 41227349, 2025). "In terms of therapeutic applications, intervention strategies targeting SERBP1 have shown anti-tumor effects in in vitro experiments." (PMID 41227349, 2025). "Although SERBP1 exhibits a tumor-promoting effect in most tumors, it also has a tumor-suppressive function in some tumor types." (PMID 41227349, 2025). "The findings revealed significantly elevated protein expression levels of EIF4G2 and SERBP1 in tumor tissues compared to normal ovarian tissues." (PMID 38603733, 2024). "According to these functions related to genes affected by SERBP1, we conclude that SERBP1 has the ability to change tumor invasion and migration." (PMID 36213507, 2022). "SERBP1 is believed to play a crucial role in various physiological processes, including fibrinolysis, wound healing, and angiogenesis, as well as in tumor cell metastasis and invasion." (PMID 33526047, 2021). "In contrast, the mRNA and protein levels of SERBP1 in tumor tissues were significantly lower in the mimic group than in the NC group." (PMID 33526047, 2021). "BIRC5/Survivin is known as an apoptosis inhibitor, while Serbp1/Serpine-1/PAI-1 is associated with tumor invasion, and MIG6 and Cadherin 13 are known as tumor suppressors." (PMID 34371830, 2021). "High levels of Serbp1/Serpine-1/PAI-1 have also been consistently reported to predict poor prognosis in several types of human cancers and are associated with tumor aggressiveness and poor patient outcomes." (PMID 34371830, 2021). "SERBP1 expression profile, its impact on GBM patient survival, response to therapy, cancer phenotypes and tumor growth establish SERBP1 as a new oncogenic RBP in GBM." (PMID 32762776, 2020). "The median nuclear IRS score was 3 with 15% (n = 91) of tumours having a low score of 0 to 2 and 85% (n = 514) showing abundant expression of SERBP1 (IRS > 2)." (PMID 23236990, 2012).
tumor (continued). "Patients who showed abundant SERBP1 expression in the tumour had an estimated mean RFS of 84 months (95% confidence interval: 74-94) compared to 67 months (95% confidence interval: 53-81) in patients with negative/weak SERBP1 expression." (PMID 23236990, 2012). "The sphere-forming ability of SERBP1-knockout GBM cells decreases by 60%, the sensitivity to temozolomide (TMZ) increases by 2.5 times, and the tumor growth rate in nude mouse xenograft models decreases by 58%, confirming that SERBP1 is a key regulatory factor for the malignant phenotype of GBM." (PMID 41227349, 2025). "SERBP1 was also detected to promote metastasis and EMT of HCC cells, while miR-218 could repressed the pro-tumor functions of SERBP1." (PMID 37649103, 2023). "SERBP1 knockdown produced strong effects on cancer-related phenotypes and tumor growth." (PMID 32762776, 2020). "Next, we evaluated the impact of SERBP1 on tumor growth using intracranial xenografts." (PMID 32762776, 2020). "SERBP1 may contribute to development of numerous tumor types." (PMID 32762776, 2020). "Collectively, these results reveal that deacetylation of SERBP1 at K68 prevents its binding to Lipt2 mRNA, which induces its instability, leading to lower levels of its mRNA and protein in KMM cells and KS tumor cells." (PMID 38470932, 2024). "All 30 DEPs were significantly correlated with DDOST in 179 PAAD tumor tissue samples, among which 22 were strong correlations, including RPN2, SERBP1, CALU, STT3B, YWHAZ and MAPK1." (PMID 39223141, 2024). "For VPS35 the correlation between corrected spots per well VPS35-specific IFN-g T cells and tumor size was R2 was 0.56 (p = 0.03), for APRC2 the R2 was 0.78 (p = 0.02), for SERBP1 the R2 was 0.55 (p = 0.03), and for KRT8 the R2 was 0.64 (p = 0.02)." (PMID 33976232, 2021). "Together, these results are a step toward understanding the multifunctional nature of SERBP1 and determining the structural underpinnings of its diverse physiological roles in healthy cells as well as its aberrant function in GBM and other tumor types." (PMID 34631798, 2021). "By promoting SERBP-1-dependent lipid metabolism, Treg cells inhibit CD8+ T cells to produce IFN-γ, maintain the immunosuppression of tumor-related macrophages, and coordinate the tumor-related immunosuppression microenvironment." (PMID 31519198, 2019). "Therefore, we can clearly conclude that SERBP1, as an RBP, has important regulatory functions in gene translation and tumor progression." (PMID 36213507, 2022).